MMP3 (matrix metallopeptidase 3)
Diseases named in the same sentence as MMP3 in open-access papers (continued):
Sharing a sentence is not in itself a finding about the gene and the disease.
tumor (continued). "The family of matrix metalloproteinases (MMPs) is also involved in various physiological processes such as inflammation, cancer, and wound healing; among them, MMP14 and MMP3 are involved in tumor progression." (PMID 37960213, 2023). "Some studies reporting that MMP3 exhibits anti-tumour activities depending in a substrate-depend manners." (PMID 37024866, 2023). "These included MMP3, with the corresponding gene also found to be amplified in the primary tumour, and the proinflammatory cytokine TNF-α." (PMID 37045997, 2023). "Tumor oncosomal MMP3 is transferred to recipient cells and alters transcriptional programs, such as cellular communication network factor 2 (CCN2) expression, in the tumor microenvironment." (PMID 36671802, 2023). "These factors will restrict tumor progression; MMP-3 demonstrates tumor suppression properties in such a case." (PMID 37513440, 2023). "Loss of FBXW7 promoted tumor proliferation, invasion and migration ability via VEGFA and MMP3 activation through ERK phosphorylation." (PMID 36991467, 2023). "We observed that the MMP3 expression level was significantly lower in high-stage tumor samples compared with low-stage samples." (PMID 37940644, 2023). "While modulating growth factors (e.g., transforming growth factor), MMP-3 stimulates the proliferation of cancer cells and tumor progression." (PMID 37513440, 2023). "It has been reported that MMP3 is modulated by several microRNAs (miRNAs and miRs), which regulate cell motility, metastasis, and tumor prognosis." (PMID 37893141, 2023). "MMPs can be divided six subfamilies, of which MMP1 and MMP13 are collagenases and MMP3 and MMP10 are stromelysins, which have long been associated with tumor invasion, metastasis and angiogenesis." (PMID 36824434, 2023). "Following carboplatin treatment, CAFs increased their expression of numerous MMP genes (Mmp2, Mmp3, Mmp13, Mmp14, Mmp27); proteases involved in the degradation of the tumor-supporting matrix." (PMID 37660083, 2023). "This is in connection with the local release of these enzymes in the tumor microenvironment; therefore, MMP-3 can be easily detected in saliva but is less represented in systemic circulation." (PMID 36547091, 2022). "COL11A1 is also associated with tumor aggressiveness and poor clinical outcomes via the TGF/β1/MMP3 axis." (PMID 35681617, 2022). "In contrast, another study showed that tumor formation was decreased in MMP-3-expressing transgenic mice." (PMID 36741729, 2022). "MMP-9), stromelysin-1 (MMP-3—only in tumor cells), and matrilysin (MMP-7), membrane type MMP-14 (only in regressed lesions)." (PMID 35626397, 2022). "MMP-3 (also known as stromelysin-1) has been reported to enhance the migratory and invasive abilities of tumor cells." (PMID 35915077, 2022). "Meanwhile, a higher MMP-3 expression in OS patients was found during tumor progression from primary to metastatic OS." (PMID 35057799, 2022). "circSEC24A interference suppressed HCC cell EMT by sponging miR-421, further regulating MMP3, and inhibiting tumor growth in vivo." (PMID 35400271, 2022). "Our analysis using the HNSC dataset in the TCGA database revealed that the expression of PTGS2, MMP1, and MMP3 in tumor tissues was significantly higher." (PMID 36555343, 2022). "High MMP3-staining next to the pathological tumor vessels and in the fibrovascular areas was observed." (PMID 35216046, 2022). "MMP-3 was described as a bifunctional protein, which has not only proteolytic properties but is also a transcriptional factor with a major role in tumor progression." (PMID 36547091, 2022). "In summary, our study shows that HDAC11 inhibits tumor metastasis in CRC through suppressing MMP3 expression." (PMID 35399729, 2022). "It is possible that MMP3 triggers tumor metastasis and the expression of MMP3 decreases after the tumor metastasizes." (PMID 36338624, 2022). "Scientific data suggested that the salivary levels of MMP-3 are also well correlated with the tumor stage." (PMID 36547091, 2022).
tumor (continued). "MMP3 has been reported to promote tumor invasion and metastasis in a variety of tumors, including HCC." (PMID 35400271, 2022). "It contributes to tumor invasion and progression by the secretion of MMP3 and pro-inflammatory cytokines." (PMID 33417986, 2021). "MMP-2 and MMP-3 have the ability to degrade collagen II, IV, IX, X, XI, and gelatine, which is known to be critical for tumor invasion and metastasis." (PMID 34078895, 2021). "The NK-exosome-treated tumor group showed a meaningful reduction in the expression of Bmi-1, MMP-3, IL-1β, IL-6, TNF-α, Bax, and Bcl-xL compared with the tumor group." (PMID 34527741, 2021). "Candesartan suppressed tumor cell proliferation and migration by modulating Cyclin D1, MMP3/9, and E-cadherin." (PMID 34121975, 2021). "This is further supported by gene expression analysis, where CAFs isolated from Osm−/− tumours exhibited decreased inflammatory gene expression (e.g. Il6, Mmp3, Has2 and Osmr) but increased myofibroblast gene expression (e.g. Acta2, Itgav and Fn1)." (PMID 34921158, 2021). "Generally, increased expression of MMP-1, MMP-2, MMP-3, MMP-7, MMP-9, MMP-13, and MMP-14 are associated with cancer advancement, which relates to poor cell differentiation, tumor invasion, distant metastasis, and poor prognosis." (PMID 33892690, 2021). "We recently showed that MMP3 in extracellular vesicles, including exosomes, can promote tumor growth." (PMID 33562088, 2021). "Gene expression analysis of PIP-expressing 4T1 cells (4T1-PIP) revealed that genes associated with tumor metastasis such as CCL7, MMP3 and MMP13, were significantly upregulated in 4T1-PIP cells when compared to the empty vector control (4T1-EV) cells." (PMID 33777801, 2021). "These proteins (THBS1, FBLN1, EDIL3, QSOX1, ACTN4, MMP3) also displayed differential mRNA expression in CRC compared to healthy intestine in the CRC TCGA dataset, and are implicated in tumour growth and metastasis regulation." (PMID 33802764, 2021). "Current studies on MMP-3 mainly focus on tumor migration and central nervous system (CNS) development, such as axon growth and remodeling." (PMID 34276395, 2021). "Our previous study found that the expression of MMP-3, 10, 12 and 13 was importantly up-regulated in tumors of UC after RT, which suggested strong tumor metastasis characteristics in UC cells after RT." (PMID 33289586, 2020). "Later studies have shown that matrix metalloproteinase 3 (MMP3) was a bifunctional protein that acted as a proteolytic enzyme and a transcriptional factor, playing crucial roles in tumor progression." (PMID 32429403, 2020). "MMP3 is expressed primarily by stromal cells, including fibroblast cell and tumor-infiltrating macrophages." (PMID 32922541, 2020). "In the favorable ccrcc2_3 subtypes, miR-204-5p was strongly upregulated, predicted long OS, and repressed several targets that are involved in tumor invasiveness and metastasis (MMP3, MMP9, AURKB, FBN2, ITGB4, SPDEF)." (PMID 32915890, 2020). "Both mRNA and protein levels of MMP‐3 were found downregulated in tumor cells from IL‐22−/−/PyMT mice compared to control mice." (PMID 31725949, 2020). "In the present paper, the areas under the ROC curve were evaluated in order to determine the diagnostic utility of MMP-3 and MMP-10 used separately and in combination with the commonly used BC tumor marker (CA 15-3)." (PMID 33371324, 2020). "In conclusion, EVs enriched with moonlighting metalloproteinase MMP3 are transmissive, pro-tumorigenic, and induce cellular communication network factor 2, which involves tumor–stromal interaction and progression." (PMID 32260433, 2020). "This study indicated that knockout of Mmp3 results in a significant inhibition of tumor growth in vivo, cellular migration and invasion in vitro." (PMID 32429403, 2020). "Considering tumour differentiation degree, MMP‐3 levels were higher after RT in grade I and III tumours." (PMID 31568637, 2020).
tumor (continued). "We generated MMP3-knockout (KO) cells using the CRISPR/Cas9 system from rapidly metastatic LuM1 tumor cells." (PMID 32429403, 2020). "Our study indicates for the first time that aggressive cancer cells can release EVs enriched in MMP3 that potentially penetrate the tumor microenvironment, cross biological barriers, and become enriched in distant organs." (PMID 32260433, 2020). "LCM from SUM159 tumor-bearing mice contained 16 unique proteins relative to other LCM conditions, including the metastasis-associated proteins CCL7, FGFR4, GM-CSF, MMP3, thrombospondin-1 and VEGF." (PMID 31936750, 2020). "The protein levels of vimentin, MMP‐13, and MMP‐3 markedly decreased in the tumor tissues grown from HeLa cells in the RES pretreatment and treatment mouse models compared to those in their respective control groups." (PMID 33040485, 2020). "It is conceivable that the knockout of MMP3 can efficiently interrupt the pro-malignant communication between tumor and stroma." (PMID 32260433, 2020). "Many of the members of MMPs family have been investigated as tumor markers, so we further explored the clinical significance of serum MMP3 in NPC." (PMID 32922541, 2020). "In other words, we aimed to investigate a mechanism by which vesicular MMP3 promotes tumor progression in vitro and in vivo." (PMID 32260433, 2020). "Such proteins activated by MMPs strengthen our in vitro findings that MMP3 can foster tumor development by modulating the activities of many signaling pathways and their receptors." (PMID 32429403, 2020). "GAL protein was stained on the cell membrane and cytoplasm in tumor tissues, and MMP3 protein was stained on the cell cytoplasm in tumor tissues." (PMID 31793228, 2020). "Western blot results revealed that the levels of p‐STAT3 (Tyr705), vimentin, MMP‐13, and MMP‐3 decreased in the tumor tissues grown from HeLa cells in the RES pretreatment and treatment groups, compared with those in the respective control groups." (PMID 33040485, 2020). "The core dynamic DEGs (Mnda, Cyp1b1, Comp, Phex, Mmp3, Tnfrsf1b, Fbln5, and Nfkb2) had been reported to be closely related to the development and metastasis in tumor and cancer progress." (PMID 33042984, 2020). "MMPs are crucial mediators in mammary gland remodelling, with ectopic expression of Mmp3 being reported to induce not only supernumerary branching and eventual tumours, but increased production of reactive oxygen species and EMT." (PMID 32942660, 2020). "Our data indicate that exogenous MMP3 can be positioned at a higher level in the protease cascade that promotes tumor progression in the recipient cells." (PMID 32429403, 2020). "Strong MMP3 staining was mainly observed in both of tumor stroma and cancer cell nests, and the weak staining was observed in some areas of metaplasia with atypical hyperplasia." (PMID 32922541, 2020). "Our finding indicated that arctigenin decreased the expression of tumor-derived cytokines, including GM-CSF, MMP-3, MMP-9 and TSLP." (PMID 32887217, 2020). "The CRISPR/Cas9-mediated knockout of MMP3 showed significant anti-tumor effects such as the inhibition of migration and invasion of tumor cells, and a reduction in CCN2/CTGF promoter activity and fragmentations in vitro." (PMID 32260433, 2020). "The positive expression rates of ANO1, GAL, and MMP3 in ESCC tumor tissues were significantly higher compared to those in normal tissues (all P at <.001)." (PMID 31793228, 2020). "We have shown MMP3 to be localized in the border area and both sides of the tumor and stroma boundary in the LuM1 allograft model." (PMID 32260433, 2020). "An inverse correlation was found between the amount of muscle IL-6, the amount of circulating adiponectin and the amount of tumour MMP3." (PMID 32472095, 2020). "Combined with the increase in DKK3 and MMP3 expression seen in tumor tissue, the demonstration of aberrant activation of LEF1 in the current study adds OSA to the range of cancers that exhibit aberrant Wnt activity." (PMID 32854182, 2020).
tumor (continued). "We here investigated the roles of MMP3-rich EVs in tumor progression, molecular transmission, and gene regulation." (PMID 32260433, 2020). "It was emphasized that active MMP-3 becomes a potent activator of proMMP-9 in a tumor cell model only when its concentration exceeds that of TIMP-1." (PMID 32455575, 2020). "MMP3 is a proteolytic enzyme, as well as a transcriptional factor that plays a crucial role in tumor progression." (PMID 32429403, 2020). "We also have shown that MMP3 was distributed at the tumor–stroma border area and immunostained in cell nuclei in the tumor allograft mouse model." (PMID 32260433, 2020). "The abundant release of MMP3-EVs from LuM1, shown in the current study, is consistent with such molecular localization in vivo involving tumor–stroma interaction." (PMID 32260433, 2020). "Knockdown of WNT2 expression suppressed cancer cell growth, reduced cellular invasion and migration, reduced β-catenin target-gene expression (MMP3/9) in vitro, and inhibited xenograft tumor growth in vivo." (PMID 32699215, 2020). "Our results show a correlation between MMP‐3 levels and menopausal status, tumour classification, differentiation degree and E‐cadherin presence." (PMID 31568637, 2020). "In contrast, a study by Mehner and colleagues found in human PDAC tissue biopsies a strong correlation of MMP3 and RAC1B expression levels in all tumor stages and a significant association of the subcellular distribution of RAC1B with patient outcome." (PMID 31817229, 2019). "After macrophage infusion, the collagen content in tumours was significantly reduced, while the expression of MMP3, MMP14 and MMP15 was increased." (PMID 31570753, 2019). "Overexpressed proteolytic enzymes MMP1 and MMP3 romote tumor growth and vascularization by enhancing extracellular matrix degradation in tumor cell microenvironments." (PMID 31717665, 2019). "The proportion of MMP3+ cells in M/Ms (white arrow) increased from 29.9% (day 1) to 94.2% (day 21) after tumor cell inoculation (3.22-fold, P < 0.0001)." (PMID 30616691, 2019). "For example, the overexpression of the serine protease matriptase in human carcinoma cells regulates MMP-3 activity, promoting proliferation and angiogenesis of tumor tissues by degradation of surrounding ECM." (PMID 31921634, 2019). "Compared with the expression of MMPs by tumor cells, MMP3 expression by M/Ms was 114.2-fold higher (P < 0.0001), while MMP9 production was only 10.9-fold higher (P < 0.001)." (PMID 30616691, 2019). "For example, complete deletion of ETS2 from epithelial and stromal cells in breast tumors leads to early hyperplastic growth and tumor formation by affecting MMP-3 and MMP-9 in macrophages in TME." (PMID 31075939, 2019). "It regulates levels of signalling proteins such as COX-2 and MMP3, which both have documented functions in tumour development." (PMID 30602942, 2018). "Relevantly, the tumour metastasis PCR array analysis pointed out MMP3 as one of the most down-regulated targets of AA6." (PMID 29988033, 2018). "The MMP-3-sensitive probe specifically targeted the tumor mass, with signals detected also at liver and kidney." (PMID 29390034, 2018). "Taken together, MMP-3 activity was primarily localized at the boundary of tumor mass and the adjacent connective tissue, an area that was also infiltrated by inflammatory monocytes." (PMID 29390034, 2018). "D6 is a chemokine decoy receptor which sequester pro-inflammatory chemokines while both CXCL7 and MMP3 can degrade the extracellular matrix and promote tumor growth and metastasis." (PMID 30237863, 2018). "During tumorigenesis, MMP-3 is a key candidate for regulating tumor-host interactions, which facilitate early-stage breast carcinogenesis." (PMID 29390034, 2018). "If CLDN8 has a higher expression measurement than MMP3 in a sample, the sample is identified as a normal sample; otherwise, a tumor sample." (PMID 28427173, 2017).
tumor (continued). "In epithelial components, MMP-3 staining was intensively positive in tumor cells and higher than that in normal glands." (PMID 28831065, 2017). "Here, we report that adipocytes increase the invasive ability of tumor cells by producing exosomes with a high level of MMP3." (PMID 29137230, 2017). "From these gene pairs, we selected a gene pair (CLDN8 and MMP3) with the largest reversal degree between the normal and tumor samples, defined as the signature." (PMID 28427173, 2017). "After transfer, MMP3 activates MMP9 in 3LL tumor cells, which improves the invasive ability of 3LL tumor cells." (PMID 29137230, 2017). "After fusion with tumor cells, adipocyte-derived exosomes transfer MMP3 into tumor cells and enhance the invasive ability of tumor cells by activating MMP9." (PMID 29137230, 2017). "Although MMP3 mediates tumor metastasis, few publications suggest that MMP3 promotes tumor invasion by directly degrading the extracellular matrix." (PMID 29137230, 2017). "Functionally, MMP-3 was linked to cell migration in invasion assays with MMP-3 silenced AGS cells, even MMP-3 derived from tumor-associated myofibroblasts was sufficient to promote AGS cell migration." (PMID 28398251, 2017). "Our results show that the oleate-induced autocrine production of PTX3 enhanced MMP-3 and vimentin expression and tumor/endothelial cell interactions to promote the metastatic seeding of tumor cells in the lungs." (PMID 28489600, 2017). "Oleate-induced PTX3 enhanced the expression of vimentin and matrix metalloproteinase-3 (MMP-3) to regulate tumor invasion." (PMID 28489600, 2017). "Increased MMP3 protein levels were noted in tumor tissues from obese patients, and MMP3 protein levels were positively correlated with MMP9 activities." (PMID 29137230, 2017). "BSG (CD147, EMMPRIN) is an inducer of tumor cell associated MMPs, including MMP1, MMP2, MMP3, and MMP9." (PMID 26769849, 2016). "Although both IL-17A and MMP-3 are known to be involved in the initiation and progression of tumor cells, their interaction has yet to be determined." (PMID 26850593, 2016). "Since previous studies have shown that MMP-3 is capable of stimulating spontaneous tumor development in mammary gland and lung, knowledge of MMP-3 regulation is of importance for developing therapeutic strategies." (PMID 26850593, 2016). "Fibroblasts-derived MMP-3 is a necessary mediator of tumor vascularization and tumor progression, and thus plays an important role in mechanisms that modulate tumor metastasis." (PMID 27271600, 2016). "In this study we were able to distinguish a statistically significant increase of MMP-3 and uPA produced by the tumor cells in breast cancer tumor samples." (PMID 27975070, 2016). "In our hands, overexpression of MMP-3 and uPA in tumor cells, and perhaps with a further contribution from the mononuclear infiltrate and stroma, would be directly related to metastasis in ganglia." (PMID 27975070, 2016). "The same pattern was apparent here also, with heightened MMP-3 mRNA found only in the presence of BM-MSC together with control tumour cells." (PMID 25596732, 2015). "Here we identify matrix metalloproteinase 3 (MMP3) as a potential target within all three of these tumor types." (PMID 26807201, 2015). "MMP3 has been well-recognized as an important player in tumor initiation, strongly based on studies using immortalized epithelial cell lines or transgenic mouse models." (PMID 26008967, 2015). "It was found that the expression of MMP-3 in MSI-L/MSS CRC tumours was greater than in MSI-H tumours, in which the levels of active MMP-9 were also lower, possibly because of a lower synthesis of MMP-3." (PMID 25932044, 2015). "Here, we observed a significant positive correlation between MMP3 expression and malignant phenotype and confirmed this observation in multiple tumor models." (PMID 26008967, 2015). "Next, we sought to molecularly alter tumor-derived MMP3 levels in order to specifically focus on the role of MMP3 in tumor progression." (PMID 26008967, 2015).